IAPP (islet amyloid polypeptide)
Diseases named in the same sentence as IAPP in open-access papers (continued):
Sharing a sentence is not in itself a finding about the gene and the disease.
Cognitive impairment (7 papers, 2012 to 2024). Abnormal cognition is characterized by deficits in thinking, reasoning, or remembering. "Compared with tau fibrils, intrahippocampal injection of IAPP-tau mixed strains into tau P301S transgenic mice significantly promoted the spread of tau pathology and induced more severe synaptic loss and cognitive deficits." (PMID 39107835, 2024). "Intrahippocampal injection of tau fibrils formed in the presence of IAPP, into tau P301S transgenic mice, triggered the spread of tau pathology, synaptic loss, and cognitive deficits." (PMID 39107835, 2024). "Intrahippocampal injection of the IAPP-tau strain into the tau P301S transgenic mice substantially promoted the spreading of tau pathology and induced more severe synapse loss and cognitive deficits, when compared with tau fibrils." (PMID 35093145, 2022). "In addition, a GV on chromosome 12 within the IAPP/SLCO1A2 genes (rs73069071) was shown to modify the association between cortical Aβ deposition on AD-related cognitive impairment and temporal lobe atrophy." (PMID 37085326, 2023). "Lastly, the effect of IAPP on tau pathology and cognitive impairments was determined by injecting the IAPP-tau fibrils and IAPP fibrils into the hippocampus of tau P301S mice." (PMID 35093145, 2022). "The effect of IAPP-tau PFFs on tau pathology and cognitive impairments was further determined by injection of the PPFs into the hippocampus of tau P301S mice." (PMID 35093145, 2022). "Brain tissue of T2DM patients exhibiting cognitive impairment contains deposits of amylin [islet amyloid polypeptide (IAPP)], a peptide hormone synthesized and co-secreted with insulin by pancreatic β cells." (PMID 34200240, 2021). "However, intraperitoneal injection of IAPP or its analog pramlintide was reported to remove Aβ from the brain and reduce cognitive impairment in AD animal models, indicating a potential protective role of IAPP against Aβ pathology." (PMID 35093145, 2022). "IAPP oligomer and 3A oligomer mimics vaccinated mice showed a relatively low titer as compared to Aβ oligomer and Aβ fibril vaccinated groups, yet retaining their efficacy in preventing cognitive deficits and amyloid deposition." (PMID 22866920, 2012). "Second, the study did not evaluate the islet amyloid polypeptide, which could also be associated with cognitive impairment." (PMID 34746146, 2021). "Oligomer mimics from 3A peptide, Aβ, islet amyloid polypeptide (IAPP), and Aβ fibrils were used to vaccinate Tg2576 mice, which develop a progressive accumulation of plaques and cognitive impairment." (PMID 22866920, 2012).
pancreatic cancer (7 papers, 2012 to 2025). "The serum level of IAPP was higher in pancreatic cancer patients than in the diabetic population or healthy controls." (PMID 37509329, 2023). "Regarding IAPP, in two pancreatic cancer cases, its expression levels in both cancerous and adjacent tissues were nearly identical." (PMID 37941546, 2023). "However, pancreatic cancer induces beta-cells to selectively secrete IAPP." (PMID 37509329, 2023). "Five mRNAs were shared between the two datasets, with SLC3A1 and IAPP down-regulated whereas CXCL14, ANLN, and TPRS1 up-regulated in pancreatic cancer." (PMID 33925948, 2021).
Hyperinsulinemia (6 papers, 2005 to 2024). An increased concentration of insulin in the blood. "The compensatory hyperinsulinemia arising due to insulin resistance leads to a higher production of hIAPP and increases endoplasmic reticulum stress, which exacerbates β-cell demise, in turn leading to greater insulin/IAPP production in the surviving β-cells." (PMID 33467592, 2021). "Chronic hyperinsulinemia, in concurrence with other factors such as lipotoxicity and increased islet amyloid polypeptide secretion, eventually leads to islet dysfunction-characterized by an initial increase in β-cell proliferation and islet mass, followed by apoptosis-leading to the onset of T2DM." (PMID 33996878, 2021).
cognitive decline (5 papers, 2019 to 2023). "To conclude, our study aimed to investigate whether levels of uIAPP and total IAPP in CSF and plasma are altered in AD patients and if these levels are associated with AD biomarkers, cognitive decline and BBB permeability." (PMID 31206565, 2019). "Our next step was to investigate whether cognitive decline or AD biomarkers were associated with uIAPP or total IAPP levels." (PMID 31206565, 2019). "Our study demonstrates an APOE4 allele-dependent decrease in IAPPO-IgA levels and that IAPP-Igs are associated with AD pathology biomarkers and cognitive decline, specifically in APOE4 non-carriers." (PMID 36835187, 2023). "Furthermore, plasma IAPP-Ig levels, especially IAPP-IgA, correlated with cognitive decline, C-reactive protein, cerebrospinal fluid Aβ and tau, neurofibrillary tangles, and brain IAPP exclusively in APOE4 non-carriers." (PMID 36835187, 2023). "Furthermore, aggregation of islet amyloid polypeptide (IAPP), a hormone secreted by β cells and Aβ plaques, may cause interaction with phosphorylated tau (p-tau) and damage to the neuronal structure and function, particularly synapses; this can lead to a cognitive decline in Alzheimer's patients." (PMID 33101293, 2020).
prediabetes (5 papers, 2019 to 2023). "Rank-rank hypergeometric overlap analysis was used to compare the transcriptome of islets from human or rodent IAPP transgenic mice vs humans with prediabetes or type 2 diabetes." (PMID 34554282, 2022). "IAPP and insulin are co-secreted from β-cells and since insulin secretion is increased in prediabetes to compensate for increased insulin demand, IAPP secretion is increased as well." (PMID 30989320, 2019). "Among other mechanisms, such as increased IAPP secretion during prediabetes or insufficient processing of IAPP as found in failing human islet grafts, IAPP is also one of the strongest activators of the NLRP3 inflammasome, which leads to activation and secretion of mature Interleukin 1β (IL-1β)." (PMID 32131431, 2020).
tauopathies (5 papers, 2014 to 2022). "Furthermore, intracerebral injection of synthetic IAPP fibrils initiated tauopathy in the brain of tau P301S transgenic mice." (PMID 35093145, 2022).
viral infection (5 papers, 2013 to 2025). "Other amyloid proteins, including ⍺Syn, islet amyloid polypeptide (IAPP), and semen enhancer of viral infection (SEVI) also show enhanced amyloidogenesis in the presence of CsgA in vitro." (PMID 38041542, 2025). "Numerous environmental factors such as not only viral infection but also chronic stress, overnutrition which leads to “gluco- and lipotoxicity,” islet amyloid and islet amyloid polypeptide (IAPP) toxic oligomer disposition in islets and bacterial LPS alone or in concert lead to islet inflammation." (PMID 38027145, 2023).
dementia with Lewy bodies (4 papers, 2018 to 2023). "However, there is no study on the role of DNSP11 in amyloid formation, whether α-synuclein is involved in Lewy body disease, Aβ is involved in AD, or IAPP is involved in islets in T2DM." (PMID 36671553, 2023). "PMDs develop and progress with a distinctive deposition of misfolded proteins such as tau and β-amyloid (Aβ) in AD, α-synuclein in PD and dementia with Lewy bodies (DLB), or amylin (also named islet amyloid polypeptide (IAPP)) in T2DM." (PMID 33832546, 2021).
dementia (3 papers, 2017 to 2020). Loss of intellectual abilities interfering with an individual's social and occupational functions. "However, the experimental data on the interaction between IAPP and ApoE are very scarce in spite of the apparent importance of ApoE in IAPP-related pathologies and the crosslink between IAPP pathologies and AD as well as other types of dementia." (PMID 31947546, 2020).
Glucose intolerance (3 papers, 2018 to 2023). Glucose intolerance (GI) can be defined as dysglycemia that comprises both prediabetes and diabetes. "β-cell autophagy inhibition leads to glucose intolerance and loss of β-cell mass in human IAPP-expressing mice and inducing autophagy facilitates the clearance of IAPP and improves β-cell activities." (PMID 34829881, 2021). "In addition, islet amyloid polypeptide (IAPP) levels have been commonly demonstrated in patients who are obese or who display damaged glucose secretion or glucose intolerance." (PMID 29682407, 2018).
amyotrophic lateral sclerosis (2 papers, 2022 to 2023). Amyotrophic lateral sclerosis (ALS) is a neurodegenerative disease characterized by progressive muscular paralysis reflecting degeneration of motor neurons in the primary motor cortex, corticospinal tracts, brainstem and spinal cord. "For example, activation is induced in AD via Aβ, in Diabetes type II (T2D) via IAPP, in PD via α-synuclein and in amyotrophic lateral sclerosis (ALS) through SOD1." (PMID 35877764, 2022).
Cachexia (2 papers, 2017 to 2020). Severe weight loss, wasting of muscle, loss of appetite, and general debility related to a chronic disease. "Furthermore, tumor-derived factors such as islet amyloid polypeptide (IAPP) contribute to both cachexia and the loss of appetite." (PMID 28241470, 2017).
neuropathy (2 papers, 2023 to 2024). A disorder affecting the nervous system that manifests with pain, tingling, numbness, and/or muscle weakness. "Intriguingly, T2DM patients with neuropathy had significantly more IAPP-positive oligomers in the skin compared with controls." (PMID 36917177, 2023). "Given the suggested role for oligomeric IAPP in diabetic complications such as neuropathy, it is tempting to speculate that the attenuated IAPP clearance seen in APOE4 carriers may be implicated in this link between APOE4 and diabetic complications." (PMID 39062913, 2024). "Aggregation of IAPP is required to exert its damaging effect on neurons in vitro, and blocking hIAPP aggregation, using the small molecule inhibitor anle145c, prevented hIAPP-induced neuropathy in vivo." (PMID 36917177, 2023). "Importantly, the aggregation of IAPP is required to induce these signs of neuropathy." (PMID 36917177, 2023). "Indeed, we identified that hIAPP-induced neuropathy does not involve the IAPP/CGRP receptor." (PMID 36917177, 2023).
synucleinopathies (2 papers, 2020 to 2022). "It has been shown that IAPP can accelerate α-synuclein amyloid formation in vitro and the interaction between IAPP and α-synuclein in the pancreatic β cells of the patients with synucleinopathies has been detected." (PMID 32116510, 2020).
systemic amyloidosis (2 papers, 2020 to 2021). "First, fibril proteins of localized amyloid forms, for example Aβ in brain and IAPP in islets of Langerhans, are synthesized by cells close to deposition sites, whereas fibril proteins in systemic amyloidosis are synthesized far from the deposition site, to where they are transported by the blood." (PMID 33274477, 2021).
autoimmune disorders (1 paper, 2019). "Owing to islet amyloid formation not found in all T2DM patients and a limited number of studies, we cannot directly find more evidence that patients with IAPP deposition defend against localized or systematic autoimmune diseases." (PMID 31993048, 2019).
brain cancer (1 paper, 2005). A primary or metastatic malignant neoplasm affecting the brain. "Of particular interest are: FGF9 which may stimulate the growth of prostate cancer, brain cancer and endometrium; and IER3 (IEX-1), PHLDA2 (TSS3), IAPP (amylin), and SST, all of which may play roles in apoptosis." (PMID 15691381, 2005).
breast carcinoma (1 paper, 2024). "IAPP was an ICR target for the diagnosis and treatment of breast cancer, which provides a theoretical basis for the treatment of breast cancer." (PMID 39654888, 2024). "Our experimental results also proved that IAPP is an immune cuprotosis gene and downregulation of IAPP mediated copper to promote the viability and function of CD8+T cells through NF-κB to play an anti-breast cancer role." (PMID 39654888, 2024).
COVID-19 (1 paper, 2023). A disease caused by infection with severe acute respiratory syndrome coronavirus 2. "Endocrine-specific genes (e.g., HSD3B2, INS, IAPP, TSHR, FOXE1, LEP, and CRYGD) were deregulated in COVID-19 cases in an organ-specific manner." (PMID 37246981, 2023).
disc degeneration (1 paper, 2017). "Thus, the results demonstrated that the gene expression of IAPP decreased during the process of disc degeneration." (PMID 28149534, 2017). "The results of this study indicated that abnormal expression of IAPP in the NP cellstriggers secretion of IL-1 and TNF-α, which act as pro-inflammatory cytokines that regulate MMP expression and accelerate disc degeneration." (PMID 28149534, 2017).
ganglioglioma (1 paper, 2022). A well differentiated, slow growing neuroepithelial neoplasm composed of neoplastic, mature ganglion cells and neoplastic glial cells. "Tau amyloid is associated with ganglioglioma, IAPP with neuroendocrine tumors, the N-terminus of prolactin with pituitary adenoma and ODAM with odontogenic tumors." (PMID 36232958, 2022).
Hypoglycemia (1 paper, 2024). A decreased concentration of glucose in the blood. "Although speculative, this low rate of IAPP-positive beta cells might be partially explained by the regulation for keeping petite to avoid hypoglycemia." (PMID 39028826, 2024).
memory impairment (1 paper, 2023). "Lately, it has been shown that misfolded IAPP accelerates Aβ aggregation in vitro and inoculation of misfolded IAPP into mouse brain results in more severe AD pathology and significantly greater memory impairments than in untreated animals." (PMID 37762425, 2023). "Moreover, intracerebral injection of misfolded pancreatic IAPP into the hippocampus of AD transgenic mice significantly enhanced AD pathology and memory impairment, compared to untreated animals." (PMID 37762425, 2023).
MODY (1 paper, 2022). "Specifically, SLC2A2 (GLUT2), and IAPP genes were commonly enriched in MODY, while HLA-DRB4 and HLA-DRB5 genes were underlying the enrichment with T1D." (PMID 35788821, 2022).
osteoporosis (1 paper, 2023). A condition of reduced bone mass, with decreased cortical thickness and a decrease in the number and size of the trabeculae of cancellous bone (but normal chemical composition), resulting in increased fracture incidence. "Then five key genes (CCR5, IAPP, IFNA4, IGHV3-73 and PTGER1) were identified and used as features to construct a predictive prognostic model for osteoporosis using the GSE7158 dataset." (PMID 37361541, 2023). "Immunity plays an important role in the development of osteoporosis.CCR5, IAPP, IFNA4, IGHV3-73 and PTGER1were play an important role in the occurrences and diagnosis of OP." (PMID 37361541, 2023).
osteosarcoma (1 paper, 2022). A usually aggressive malignant bone-forming mesenchymal neoplasm, predominantly affecting adolescents and young adults. "Similar to what was seen in H1299 cells, Western blot analysis demonstrated that IAPP expression in osteosarcoma cells was decreased compared to the hFOB positive control cells." (PMID 36077845, 2022).
pertussis (1 paper, 2021). A contagious bacterial respiratory infection caused by Bordetella pertussis. "The C5 and IAPP genes are predicted to be involved in neuroactive ligand-receptor interaction, Staphylococcus aureus infection, Pertussis, complement, and coagulation cascades." (PMID 34262595, 2021).
thymic lymphoma (1 paper, 2022).
Zinc deficiency (1 paper, 2015). A deficiency of the essential metal Zinc; an essential cofactor for many enzymes. "A fundamental question is what the effect of zinc-deficiency in β-cell granules is on the disease development, such as IAPP aggregation and IAPP-insulin interactions." (PMID 25649462, 2015). "Therefore, zinc deficiency due to loss-of-function ZnT8 mutations shifts insulin oligomer equilibrium toward zinc-free monomers and dimers, which bind IAPP monomers more efficiently compared to zinc-bound hexamers." (PMID 25649462, 2015).
tumor (11 papers, 2012 to 2024). "The final data demonstrated that sh-IAPP-Her2-CAR-T cells significantly restrained the tumor growth and prolonged survival in vivo (P<0.01)." (PMID 39654888, 2024). "Silencing of either ΔNp63 or ΔNp73 restored the IAPP levels, inhibiting glycolysis and inducing tumor cell apoptosis." (PMID 36077845, 2022). "Upregulating IAPP and increasing amylin inhibited tumor glycolysis and increased reactive oxygen species (ROS) production, leading to tumor cell apoptosis and tumor regression." (PMID 36077845, 2022). "Pramlintide-mediated tumor regression was shown to be mediated by metabolic reprogramming through the upregulation of IAPP." (PMID 36077845, 2022). "IAPP functions as a tumor marker for identifying pancreatic islet cell tumors." (PMID 39654888, 2024). "Four genes were associated with the tumor stage, including solute carrier family 6 member 14 (SLC6A14), polypeptide N-acetylgalactosaminyltransferase 5 (GALNT5), tetraspanin 1 (TSPAN1), and islet amyloid polypeptide (IAPP)." (PMID 34591244, 2021). "Statistical analysis revealed that downregulation of IAPP notably suppressed BRCA growth, and its combination with TTM further enhanced the anti-tumor effect (P<0.01, P<0.001)." (PMID 39654888, 2024). "Furthermore, anti-BRCA function and mechanism of islet amyloid poly-peptide (IAPP) mediated CD8+T cells were verified by means of flow cytometry, ELISA, and subcutaneous transplantation tumor model." (PMID 39654888, 2024). "Deletion of IAPP in mice did not impact their survival time in the presence of a lethal tumor burden." (PMID 39596226, 2024).
cancer (9 papers, 2012 to 2025). A tumor composed of atypical neoplastic, often pleomorphic cells that invade other tissues. "The IDEGs (SLPI, IAPP, NPY, ISG15, PLA2G2A, and HLA-DMB) in the predictive PCa risk model constructed in the present study play an important regulatory role in cancer." (PMID 36774376, 2023). "Both insulin-expressing cancer cell populations expressed beta cell, insulin, and glucose-related genes, including known neuroendocrine genes such as chromogranins, secretogranins, and IAPP (islet amyloid polypeptide)." (PMID 40438247, 2025). "The immune histochemical sections of the HPA database showed that the protein expression of SLPI, DES, IAPP, NPY, ISG15 and HLA-DMB in normal tissue was higher than that in cancer tissue, while the protein expression of PLA2G2A in normal tissue was lower than that in cancer tissue." (PMID 36774376, 2023).
neurodegenerative disease (6 papers, 2014 to 2024). A disorder of the central nervous system characterized by gradual and progressive loss of neural tissue and neurologic function. "Our studies indicated that autophagy served as an important protective mechanism in human degenerative diseases through the cellular catabolic pathways that included lysosomal degradation and recycling of proteins and organelles, and is regulated by IAPP." (PMID 28149534, 2017).
metabolic disorders (3 papers, 2018 to 2026). "The islet amyloid polypeptide (IAPP) is a peptide hormone playing key biological roles, including glucose homeostasis and regulation of food intake, conferring high therapeutic potential to treat metabolic disorders." (PMID 41898461, 2026).
vasculopathy (3 papers, 2019 to 2023). "We and others have in recent studies demonstrated a potential link between vasculopathy and islet amyloid polypeptide (IAPP)." (PMID 31206565, 2019).